CYLC1 (cylicin 1)
Description:
Plays a role in the establishment of normal sperm morphology during spermatogenesis and is required for acrosome attachment to the nuclear envelope.
Synonyms: CYCL1; SPGFX8
Tractability: PROTAC: ubiquitination databases record sites on it.
Gene: Protein-coding gene on chromosome X (83,861,126 to 83,886,699, forward strand). Ensembl gene ENSG00000183035.
Subcellular location: Cytoplasm, cytoskeleton, perinuclear theca, calyx; Cytoplasm, cytoskeleton, perinuclear theca
Subcellular location (Human Protein Atlas): Calyx; Perinuclear theca
Gene Ontology:
Molecular function: protein binding; structural molecule activity; structural constituent of cytoskeleton
Biological process: acrosome assembly; spermatogenesis; cytoskeleton organization
Cellular component: acrosomal matrix; cytoskeletal calyx; nucleus; perinuclear theca; sperm glycocalyx; sperm head
Homologues: Orthologues: chimpanzee CYLC1 (99% identical), macaque CYLC1 (89% identical), rabbit CYLC1 (62% identical), pig CYLC1 (61% identical), rat Cylc1 (42% identical), mouse Cylc1 (39% identical). Paralogues in human: CYLC2 (20% identical).
Diseases named in the same sentence as CYLC1 in open-access papers:
CYLC1 is named in the same sentence as 2 diseases in open-access papers, as found by Europe PMC text mining. Sharing a sentence is not in itself a finding about the gene and the disease. The quoted sentences say what the papers report.
male infertility (4 papers, 2023 to 2025). The inability of the male to effect fertilization of an ovum after a specified period of unprotected intercourse. "Extending to humans, we suggest that CYLC1 variants contribute to male infertility, especially when combined with certain variants of other male infertility-associated genes." (PMID 38573307, 2024). "To explore the clinical relevance of cylicin-1 deficiency to human male infertility, we performed WES analysis in a large cohort of more than 500 infertile patients with sperm head deformities." (PMID 38573307, 2024). "We further evaluated whether CYLC1-associated male infertility could be overcome by assisted reproductive technologies (ART)." (PMID 38573307, 2024). "This hypothesis is supported by our finding that Cylc1 deficiency causes subfertility in male mice, while the loss of both Cylc2 alleles results in male infertility." (PMID 38013430, 2023). "Knockout of Cylicin 1 leads to low fertility in male mice, and the knockout of any two copies of Cylicin 1 and Cylicin 2 can result in male infertility." (PMID 39765560, 2024). "In this study, we thoroughly reveal the physiological role of cylicin-1 and explore its clinical relevance to male infertility." (PMID 38573307, 2024).
infertile (2 papers, 2023 to 2024). "A CYLC1 variant was identified from a WES (whole exome sequencing) study of infertile patients with sperm head deformities." (PMID 38573307, 2024). "Nineteen individuals carrying a CYLC1 variant identified from >500 infertile men with sperm head deformities." (PMID 38573307, 2024). "By recruiting a large cohort (>500 infertile men with sperm head deformities), a CYLC1 variant was identified in 19 individuals by WES." (PMID 38573307, 2024). "WES (whole exome sequencing) of more than 500 Chinese infertile men with sperm head deformities was performed and a CYLC1 variant was identified in 19 patients." (PMID 38573307, 2024). "The significance of our findings is supported by the identification of CYLC1/2 variants in an infertile patient who presents similar structural anomalies in sperm cells." (PMID 38013430, 2023). "Furthermore, exome sequencing identified an infertile man with a hemizygous variant in CYLC1 and a heterozygous variant in CYLC2, displaying morphological abnormalities of the sperm including the absence of the acrosome." (PMID 38013430, 2023). "As loss of two Cylicin alleles causes fertility defects in mice, we next addressed whether infertile men also display variants in CYLC1/CYLC2." (PMID 38013430, 2023). "Overall, the identification and detailed characterization of further patients with variants in CYLC1 and CYLC2 is warranted to draw firm conclusions on the effect of variants in these genes on spermiogenesis and infertility." (PMID 38013430, 2023).